PKD1L2 (polycystin 1 like 2 (gene/pseudogene))
Description:
May function as a G protein-coupled receptor.
Synonyms: KIAA1879; PC1L2
Tractability: Antibody: UniProt predicts a signal peptide or a membrane-spanning region.
Gene: Protein-coding gene on chromosome 16 (81,100,875 to 81,220,370, reverse strand). Ensembl gene ENSG00000166473.
Subcellular location: Membrane
Gene Ontology:
Molecular function: calcium channel activity; calcium ion binding; carbohydrate binding
Biological process: detection of mechanical stimulus; calcium ion transmembrane transport
Cellular component: membrane
Genetic constraint (gnomAD): Loss-of-function variants: 144 observed, 108.64 expected, observed/expected ratio (o/e) 1.33, 90% interval 1.16 to 1.52. The synonymous counts are far from expectation, so gnomAD's model fits this gene poorly and the ratio says little. Missense variants: 1,781 observed, 1,231.1 expected, observed/expected ratio (o/e) 1.45, 90% interval 1.39 to 1.5. Synonymous variants: 713 observed, 507.24 expected, observed/expected ratio (o/e) 1.41, 90% interval 1.32 to 1.5.
Homologues: Orthologues: pig PKD1L2 (65% identical), mouse Pkd1l2 (64% identical), rat Pkd1l2 (63% identical), tropical clawed frog pkd1l2 (44% identical), zebrafish pkd1l2a (37% identical), zebrafish pkd1l2b (25% identical), zebrafish pkd1a (17% identical), zebrafish pkd1l2b (11% identical), Drosophila melanogaster Pkd2 (3% identical), Caenorhabditis elegans pkd-2 (3% identical). Paralogues in human: PKD1 (19% identical), PKD1L3 (17% identical), PKDREJ (15% identical), PKD1L1 (13% identical), LOXHD1 (9% identical), DENND5B (7% identical), DENND5A (7% identical), PKD2 (4% identical), PKD2L1 (3% identical), PKD2L2 (2% identical).
Diseases named in the same sentence as PKD1L2 in open-access papers:
PKD1L2 is named in the same sentence as 14 diseases in open-access papers, as found by Europe PMC text mining. Sharing a sentence is not in itself a finding about the gene and the disease. The quoted sentences say what the papers report.
polycystic kidney disease (5 papers, 2012 to 2024). A usually autosomal dominant and less frequently autosomal recessive genetic disorder characterized by the presence of numerous cysts in the kidneys leading to end-stage renal failure. "PKD1L2 is associated with polycystic kidney disease, and RP1L1 variants are associated with several retinal diseases including occult macular dystrophy." (PMID 35653351, 2022). "Our current findings revealed that the SNPs rs4889261 and rs13339342 in PKD1L2 (encoding polycystic kidney disease 1-like 2) were marginally associated with HTG." (PMID 31937794, 2020). "Besides beingassociated with polycystic kidney disease, a study in the Korean population revealedthat a copy number variation in PKD1L2 is related with colorectalcancer predisposition." (PMID 38259032, 2024). "PKD1L2 is highly expressed in the kidney and is a suspected modifier of polycystic kidney disease, so represents a plausible genetic modifier of sickle cell nephropathy." (PMID 27711207, 2016).
breast carcinoma (3 papers, 2020 to 2024). "According to a previous study using The Cancer Genome Atlas (TCGA) dataset, overexpression of PKD1L2 mRNA is associated with improved prognosis in patients with breast cancer." (PMID 32986753, 2020). "rs386792906 (chr16:g.81253642 AG>TC) in polycystin 1 like 2 (PKD1L2), which was associated with resistance to MTX, showed the strongest association of the nine tested anti-cancer drugs among the breast cancer subgroup (P = 1.52 × 10−5, rs = 0.991)." (PMID 32986753, 2020). "Additionally, PKD1L2 features a four-mRNA modelrecently constructed for prediction of breast cancer prognosis." (PMID 38259032, 2024). "Besides, PKD1L2 was associated with resistance and sensitivity to MTX in the breast cancer and gastric cancer." (PMID 39611166, 2024). "Although the functional association between PKD1L2 and MTX is unknown, this variant may be a useful marker for predicting sensitivity to MTX, and may act as an indicator of prognosis for breast cancer in the clinical setting." (PMID 32986753, 2020).
polycystic ovary syndrome (1 paper, 2024). A disorder that manifests as multiple cysts on the ovaries. "PKD1L2 expression was detected to be among the most downregulated in the adipose tissue of polycystic ovary syndrome (PCOS) patients, suggesting that Pkd1l2 could function as a potential biomarker for PCOS diagnosis." (PMID 38786026, 2024).
kidney (2 papers, 2023 to 2024). "The polycystic kidney disease 1-like 2 (PKD1L2) gene encodes a polycystin-1-like subfamily, and the protein has ion channel segments that are highly conserved among polycystin-2 family members, suggesting that they possess cation channel functions." (PMID 39611166, 2024). "The upstream syntenic gene of FrLRR on scaffold 11 is the polycystic kidney disease 1 like 2 gene (PKD1L2), and downstream is the melanopsin-B-like protein (mBl)." (PMID 37044216, 2023).
infection (1 paper, 2024). The state of being infected such as from the introduction of a foreign agent such as serum, vaccine, antigenic substance or organism. "Similarly to the present study, these authors observed increased TMEM71 expression (2.5-, 8.7-, and 35.8-fold increases respectively after 24, 48, and 72 hours of infection) and PKD1L2 (2.8-, 9.6-, and 49.9-fold increases at 24, 48, and 72 after infection, respectively)." (PMID 38512822, 2024).
kidney disease (1 paper, 2024). "As a member of the TRPP family protein, PKD1l2 (polycystic kidney disease 1 like 2) is a cation protein comprising six transmembrane domains, eight topological domains, and one intramembrane interleaving with each other." (PMID 38786026, 2024).
PKD1L2 also shares sentences with these, for which no sentence is quoted: cancer (2 papers); autosomal dominant polycystic kidney disease (1); gastric cancer (1); neurodevelopmental disorder (1); occult macular dystrophy (1); psoriasis (1); retinal diseases (1); schizophrenia (1).